DGAT1 (diacylglycerol O-acyltransferase 1)
Diseases named in the same sentence as DGAT1 in open-access papers (continued):
Sharing a sentence is not in itself a finding about the gene and the disease.
ovarian carcinoma (6 papers, 2021 to 2025). A malignant neoplasm originating from the surface ovarian epithelium. "In conclusion, our study elucidates a novel mechanism underlying KU60019-induced ovarian cancer cell death through the miR-1273g-3p/DGAT1 regulatory axis." (PMID 40554491, 2025). "Higher levels of DGAT1 associated with worse survival in ovarian cancer patients." (PMID 40554491, 2025). "In this study, we found that higher expression of DGAT1 associated with poor survival in ovarian cancer patients, progression-free survival and postprogression survival could also be impacted by DGAT1 expression in patients." (PMID 40554491, 2025). "Elevated DGAT1 expression was reported to be correlated with worse survival in gastric cancer patients, and is significantly associated with advanced cancer stage and survival in ovarian cancer patients." (PMID 40554491, 2025). "DGAT1 expression is associated with the clinical phenotype of ovarian cancer." (PMID 34095320, 2021). "We found that DGAT1 expression is associated with ovarian cancer." (PMID 34095320, 2021). "DGAT1 is closely associated with the clinical phenotype of ovarian cancer." (PMID 34095320, 2021). "We identified DGAT1 as a potential target of miR-1273g-3p in ovarian cancer cell under KU60019 treatment." (PMID 40554491, 2025). "Our results demonstrate the antitumor effect of KU60019 in ovarian cancer depended on miR1273g-3p/DGAT1 axis." (PMID 40554491, 2025). "It was reported that overexpression of DGAT1 in ovarian cancer tissues predicted a worse outcome in ovarian cancer patients, suppression of DGAT1 reduced cell proliferation and migration." (PMID 40554491, 2025). "KU60019 induced ovarian cancer cell impairment by enhancing DGAT1 level and suppressing hsa-miR-1273g-3p level." (PMID 40554491, 2025). "Hsa-miR-1273g-3p mimics were used to investigate the relationship between DGAT1 and hsa-miR-1273g-3p in ovarian cancer cells under ATM inhibitor treatment, and cell apoptosis rate, viability, and migration were detected." (PMID 40554491, 2025). "We investigated the relationship between DGAT1 and survival of ovarian cancer patients based on level of DGAT1 in ovarian cancer tissues (Red, high expression; black, low expression)." (PMID 40554491, 2025). "Analysis of TCGA ovarian cancer datasets confirmed DGAT1 overexpression in tumor tissues compared to normal controls." (PMID 40554491, 2025). "Elevated DGAT1 levels in ovarian cancer tissues show positive correlation with advanced cancer stages." (PMID 40554491, 2025). "In current study, we found that the expression of DGAT1 was significantly suppressed in ovarian cancer cell line SKOV3 cells after ATM inhibitor KU60019 treatment." (PMID 40554491, 2025). "Collectively, these findings indicate that miR-1273g-3p mediates DGAT1-regulated apoptotic processes in ovarian cancer cells upon KU60019 treatment." (PMID 40554491, 2025). "DGAT1 expression was increased in stage IV ovarian cancer compared with stage III ovarian cancer, and overexpression of DGAT1 was more common in poorly differentiated ovarian cancer compared with well-differentiated ovarian cancer." (PMID 38500157, 2024). "After DGAT1 expression was interfered, proliferation, migration, invasion, colony forming, and tumor growth of ovarian cancer cells were inhibited." (PMID 34095320, 2021). "After the expression of DGAT1 was interfered, the proliferation, migration, invasion, colony forming, and tumor growth of ovarian cancer cells were inhibited." (PMID 34095320, 2021). "Due to bioinformatics analysis showed DGAT1 has a close relationship with ovarian cancer phenotype, and we tested DGAT1 function in ovarian cell lines on the proliferation and metastasis." (PMID 34095320, 2021). "We analyzed the correlation between DGAT1 and ovarian cancer staging, grading, vascular invasion, and prognosis by collating the information of ovarian cancer specimens from The Cancer Genome Atlas (TCGA) database." (PMID 34095320, 2021).
ovarian carcinoma (continued). "Based on DGAT1 expression levels in the ovarian cancer, samples of TCGA datasets were categorized into two groups, namely, DGAT1-low group (<11.36) and DGAT1-high group (≥11.36)." (PMID 34095320, 2021). "GSEA was used to analyze the KEGG pathways and biological function enriched because of DGAT1 expression in ovarian cancer." (PMID 34095320, 2021). "DGAT1 level elevated in multiple cancer, such as bladder cancer, myeloma, pancreatic adenocarcinoma, papillary renal cell carcinoma, ovarian cancer, and gastric cancer." (PMID 33750350, 2021). "As the immune system plays an irreplaceable role in the development of cancer, thus, TIMER website was utilized to explore the correlation between DGAT1 and immune cells in ovarian cancer." (PMID 34095320, 2021). "GSEA was carried out to determine the KEGG pathways and biological function of DGAT1 expression in ovarian cancer." (PMID 34095320, 2021). "The expression of DGAT1 was higher in advanced (p = 0.0432), poorly differentiated (p = 0.0148), and vascular invaded (p = 0.0002) ovarian cancer specimens." (PMID 34095320, 2021). "The expression of DGAT1 was elevated in advanced (p = 0.0432), poorly differentiated (p = 0.0148), and vascular invaded (p = 0.0002) ovarian cancer specimens." (PMID 34095320, 2021). "However, the regulatory effect of KU60019 on DGAT1 expression in ovarian cancer cells remains poorly characterized." (PMID 40554491, 2025). "In addition, we observed high level of DGAT1 in ovarian cancer tissues predicted a poor outcome in ovarian cancer patients." (PMID 40554491, 2025). "Finally, Kaplan-Meier analysis showed the correlation between DGAT1 level and survival in ovarian cancer patients." (PMID 40554491, 2025). "In the current study, we hypothesized that blocking DGAT1 might inhibit tumor growth, and investigated the role of DGAT1 in ovarian cancer cells in the context of ATM blockage in vitro." (PMID 40554491, 2025). "Similarly, knockdown of DGAT1 in the ovarian cancer OVCAR-5 and PEO4 cell lines inhibited cell proliferation, colonization, and migration." (PMID 38500157, 2024). "Finally, we found DGAT1 to be frequently amplified in other human cancers, a feature of many well-characterized oncogenes, most notably in up to 26% of cases of ovarian cancer." (PMID 35732120, 2022). "Thus, our findings suggest that DGAT1 is involved in the development and metastasis of ovarian cancer." (PMID 34095320, 2021). "We suggest that DGAT1 has potential implications in the treatment of ovarian cancer." (PMID 34095320, 2021). "Furthermore, the effects of DGAT1 expression on proliferation, migration, invasion, and tumor growth were studied using ovarian cancer cell lines." (PMID 34095320, 2021). "The prognosis of ovarian cancer among patients with high expression of DGAT1 was poor." (PMID 34095320, 2021). "However, the mechanism by which DGAT1 regulates the progression of ovarian cancer needs to be further studied." (PMID 34095320, 2021). "However, the role of DGAT1 in ovarian cancer during ATM inhibition remains poorly understood." (PMID 40554491, 2025). "However, the role of DGAT1 in ovarian cancer remains poorly understood." (PMID 34095320, 2021). "Therefore, we hypothesize that DGAT1 holds potential implications in the treatment of ovarian cancer." (PMID 34095320, 2021). "Therefore, DGAT1 is presumed to be a novel target for the treatment of ovarian cancer." (PMID 34095320, 2021). "In this study, ovarian cancer cells (SKOV3) were treated with an ATM inhibitor (KU60019) for 24 hours, and the fold changes of DGAT1 and hsa-miR-1273g-3p were quantified by real-time quantitative polymerase chain reaction (RT-qPCR)." (PMID 40554491, 2025). "Unexpectedly, we found that KU60019 treatment leaded to overexpression of DGAT1 in ovarian cancer tissues, but not in non-tumor cells." (PMID 40554491, 2025). "However, the role of DGAT1 in ovarian cancer is not yet elucidated." (PMID 34095320, 2021).
ZIKV infection (6 papers, 2020 to 2024). "Accordingly, the DGAT-1 inhibitor decreases inflammatory cytokine production, weight loss and mouse mortality induced by ZIKV infection." (PMID 36882750, 2023). "Moreover, we observed that inhibition of DGAT-1 inhibited the weight loss and mortality induced by ZIKV infection in vivo." (PMID 36882750, 2023). "Concurrent with reduced virus production, knockdown of DGAT1 or SOAT1 in Huh7 cells diminished viral RNA and protein level, indicating that loss of either enzyme reduced ZIKV infection rates." (PMID 39237833, 2024). "To evaluate the potential of LD inhibition to treat ZIKV infection in vivo, we infected neonatal mice (P2) with daily intraperitoneal injections of the DGAT-1 inhibitor A922500 for seven days." (PMID 37820117, 2023). "The role of LD in the innate immune response agrees with our results using the in vivo ZIKV infection model, which shows that the DGAT-1 inhibitor A922500 decreases cytokine/chemokine production in addition to impairing LD production in human neuronal cells." (PMID 37820117, 2023). "Corroborating these observations, blocking DGAT-1 reduced the biogenesis of LDs induced by ZIKV infection and decreased viral replication in neural cells." (PMID 36882750, 2023). "To advance the understanding of the role of lipid accumulation during ZIKV infection in neural cells, we analyzed the pharmacological inhibition of the DGAT-1 enzyme, which catalyzes the terminal step in TAG synthesis." (PMID 36882750, 2023). "Compared with vehicle treatment, treatment with a DGAT-1 inhibitor (iDGAT-1, A922500) markedly decreased LD accumulation triggered by ZIKV infection in a concentration-dependent manner in SH-SY5Y cells." (PMID 36882750, 2023). "The essential role of these organelles in ZIKV infection is further support by our observation showing that interference with DGAT1 enzymatic activity suppresses the dynamic of LD growth and hampers viral replication." (PMID 32528049, 2020). "Our data clearly show that ZIKV infection increases DGAT1 expression further promoting the biogenesis and growth of the placental LDs." (PMID 32528049, 2020). "Furthermore, we identified that DGAT-1 expression increases after ZIKV infection; this enzyme catalyzes the last step in triglyceride synthesis." (PMID 36882750, 2023). "Moreover, our data revealed that treatment with a DGAT-1 inhibitor also decreased mouse mortality induced by ZIKV infection." (PMID 36882750, 2023). "DGAT1, ACAT1, AGPAT1, and AGPAT2 mRNA levels were increased after ZIKV infection (albeit < 1.5-fold compared with the levels in the mock control), indicating that ZIKV infection promotes LD biosynthesis." (PMID 36405969, 2022). "Since DGAT1 expression but not its enzyme activity seemed to be critical for efficient ZIKV infection, we hypothesized that a direct interaction of DGAT1 with a viral protein is required for efficient ZIKV replication." (PMID 39237833, 2024). "Additionally, mice treated with the DGAT-1 inhibitor A922500 exhibited reduced inflammatory mediator production compared to nontreated mice during ZIKV infection." (PMID 36882750, 2023). "However, they did not directly show the impact of DGAT1 on ZIKV infection." (PMID 39449854, 2024). "Although the expression of the DGAT1, ACAT1, AGPAT2, and AGPAT1 genes, which are involved in LD biosynthesis, was activated, fatty-acid synthases (SCD1 and FASN, but not ACC1) were significantly downregulated during ZIKV infection." (PMID 36405969, 2022).
colon cancer (5 papers, 2021 to 2023). "The qPCR data showed here that DGAT1 mRNA was the major form and the two variants of DGAT2 mRNA accounted for only half of the DGAT1 mRNA levels in the human colon cancer cells." (PMID 33723275, 2021). "LPS increased TTP family, GLUT family and DGAT1 mRNA levels but decreased DGAT2a and DGAT2b expression in the human colon cancer cells." (PMID 37705049, 2023). "DGAT2 mRNA is the major DGAT mRNA in mouse adipocytes and macrophages, but DGAT1 mRNA was the major form in the human colon cancer cells." (PMID 37705049, 2023). "LPS treatment under higher concentration increased DGAT1 mRNA levels but decreased DGAT2a and DGAT2b expression in the human colon cancer cells." (PMID 37705049, 2023). "The qPCR data showed that glandless kernel extract inhibited DGAT1, 2a and 2b expression in the human colon cancer cells." (PMID 35058516, 2022). "DGATs are classified with DGAT1 and DGAT2 subfamilies in animals and additional DGAT3 subfamily in plants with DGAT2 mRNA being the major form of DGAT mRNAs in mouse adipocytes and macrophages but DGAT1 as the major one in the colon cancer cells." (PMID 35058516, 2022). "In contrast to mouse macrophages, we showed here that gossypol inhibited DGAT1 and DGAT2 expression in the human colon cancer cells." (PMID 33723275, 2021).
gastric cancer (5 papers, 2021 to 2025). A primary or metastatic malignant neoplasm involving the stomach. "Overexpression of DGAT1 is associated with poorer survival outcomes in OC and gastric cancer, whereas it correlates with improved survival in lung adenocarcinoma." (PMID 41041279, 2025). "Our results showed a highly expression of DGAT1 in gastric cancer tissues (n = 5, p = 0.0004), and tumor-infiltrating macrophages with elevated DGAT1 expression is associated with poor overall survival in gastric cancer patients." (PMID 33750350, 2021). "Inhibiting DGAT1 activity by a DGAT1 inhibitor (A922500) significantly increased early and late apoptosis of gastric cancer MKN45 cells in the presence of sodium oleate compared to A922500 alone." (PMID 38500157, 2024). "Overexpression of DGAT1 in both gastric cancer cells and tumor-infiltrating macrophages of patients with gastric cancer compared to normal tissues was associated with poor overall survival in gastric cancer patients." (PMID 38500157, 2024). "And the results revealed that mRNA expression and DNA copy number variation of DGAT1 was increased in immune cells of gastric cancer tissue other than immune cells in normal tissues." (PMID 33750350, 2021). "Collectively, increased DGAT1 expression can be detected in all types of gastric cancer patients, and high level of DGAT1 indicated a poor prognosis in gastric cancer patients." (PMID 33750350, 2021). "In this study, collected data from TCGA database reported abnormally elevated expression of DGAT1 in several types of cancer in patients, and we observed dramatic elevated level of DGAT1 in gastric cancer patients." (PMID 33750350, 2021). "Next, we investigated DGAT1 level in several gastric cancer cell lines, and human gastric mucosal epithelial cell line GES-1 was used as normal control." (PMID 33750350, 2021). "The findings of this research provide an in-depth insight into the potential role and influences involved in DGAT1 in the gastric cancer patients." (PMID 33750350, 2021). "As block DGAT1 effectively suppressed functional factors secretion in gastric cancer cell line, next we investigated cell viability after DGAT1 inhibition." (PMID 33750350, 2021). "In current study, we detected sodium oleate treatment improved DGAT1 expression in gastric cancer cell line MKN45, and NOX2 and IDO expression level also increased significantly." (PMID 33750350, 2021). "To investigate the influence of altered expression of DGAT1 to patients with gastric cancer, we compared survival time of patients depended on DGAT1 expression level." (PMID 33750350, 2021). "We performed survival analysis using Kaplan-meier plots and the results showed that higher expression of DGAT1 leads to lower overall survival (OS) rate in patients with poorly differentiated gastric cancer." (PMID 33750350, 2021). "Collectively, oleate sodium elevated DGAT1 expression in gastric cancer cell line MKN45 and DGAT1 blockade induced cell apoptosis in vitro." (PMID 33750350, 2021). "We screened the public cancer datasets to identify the expression and function of DGAT1 in gastric cancer and tumor infiltrating lymphocytes." (PMID 33750350, 2021). "Collectively, DGAT1 was highly expressed in gastric cancer tissues, and significantly decreased with the deterioration of diseases." (PMID 33750350, 2021). "Deletion and aberrant amplification of DGAT1 can be found in different types of the gastric cancer patients." (PMID 33750350, 2021). "And higher expression of DGAT1 leads to lower overall survival (OS) rate in patients with poorly differentiated gastric cancer." (PMID 33750350, 2021). "As high level of DGAT1 in gastric cancer patients indicates a poor outcome with respect to overall survival, we firstly analyzed DGAT1 expression level in cancer tissue from gastric cancer patients." (PMID 33750350, 2021). "Oleate sodium treatment increased DGAT1 expression in gastric cancer cell line MKN45." (PMID 33750350, 2021).
gastric cancer (continued). "Thus, Transcriptomic analysis and in vitro experiments were performed to investigate the role of DGAT1 in gastric cancer, as well as the potential therapy target in gastric cancer treatment." (PMID 33750350, 2021). "DGAT1 expression was significantly higher in gastric cancer cell lines AGS and MKN45." (PMID 33750350, 2021). "Finally, we analyzed ration of apoptosis, necrosis in gastric cancer cells by using flow cytometry after administration of DGAT1 inhibitor." (PMID 33750350, 2021). "Our findings suggest a potential role for DGAT1 in the gastric cancer progression and inhibiting DGAT1 might be a promising strategy in gastric cancer treatment." (PMID 33750350, 2021). "Indeed, we observed highly expression of DGAT1 in several types of cancer in patients, which was especially correlated with worse prognosis in gastric cancer patients." (PMID 33750350, 2021). "We demonstrated a worse prognosis in gastric cancer patients with elevated DGAT1 expression." (PMID 33750350, 2021). "However, much uncertainty still exists about the relationship between DGAT1 and the reactive oxygen species in gastric cancer progression." (PMID 33750350, 2021). "We analyzed DGAT1 levels in tumor-infiltrating immune cells in patients with gastric cancer." (PMID 33750350, 2021). "Among which, DGAT1 was highly expressed in patients with gastric cancer." (PMID 33750350, 2021). "The objectives of this research are to determine whether DGAT1 functionally influence gastric cancer progression and prognosis of patients, and uncover the clinic meaning of DGAT1." (PMID 33750350, 2021). "The current study describes the crucial role of DGAT1 in gastric cancer progression." (PMID 33750350, 2021). "Intervention strategies blocking DGAT1 in patients might be clinically valuable in the future gastric cancer treatment." (PMID 33750350, 2021). "Inhibition of DGAT1 may serve as a promising strategy for gastric cancer therapy." (PMID 35785165, 2022). "However, the relationship between DGAT1 and gastric cancer is still unclear." (PMID 33750350, 2021). "Thus, the present study raises the possibility that DGAT1 could be a promising biomarker and potential target for the diagnosis and treatment of gastric cancer." (PMID 33750350, 2021).